TNF (tumor necrosis factor)
Diseases named in the same sentence as TNF in open-access papers (continued):
Sharing a sentence is not in itself a finding about the gene and the disease.
metabolic syndrome (continued). "In human studies, subjects with metabolic syndrome receiving blueberry showed a significant decline in superoxide and total ROS together with a reduction of inflammatory markers and reduced gene expression of TNF-α, TLR4, and IL-6." (PMID 35898615, 2022). "OA and the metabolic syndrome are recognized as the low-grade inflammatory condition with elevations in systemic inflammatory mediators such as interleukin-1 (IL-1), interleukin-6 (IL-6), and tumor necrosis factor (TNF)." (PMID 36175967, 2022). "However, in a cross-sectional study of individuals with metabolic syndrome, plasma SAM levels were reported to be associated with increased fasting insulin levels, IR, and tumor necrosis factor-α." (PMID 36299884, 2022). "The objective of this study was to determine the relationship between prevalence of dyslipidemia and measured changes in the levels of proinflammatory cytokines (IL-6, TNF-a, and MCP-1), thiobarbituric acid-reactant substances (TBARS), and serum total antioxidant capacity (TAC) in serum samples." (PMID 36032093, 2022). "The serum TNF-α was raised in metabolic syndrome patients than the healthy controls." (PMID 34104151, 2021). "Previous studies have reported a significant link of TNF-α with the IR onset in metabolic syndrome." (PMID 34104151, 2021). "Histidine can inhibit TNF-α signaling pathway and attenuate the expression of pro-inflammatory cytokines, and it has been used to treat inflammation in obese patients with metabolic syndrome." (PMID 34938667, 2021). "In addition, a meta-analysis study demonstrated a decrease in C-reactive protein, tumor necrosis factor-α, interleukin-6, and interleukin-1 levels in statin users with metabolic syndrome and related diseases." (PMID 33202921, 2020). "The increase in TNF-α production observed in animals exposed to oxysterols may be one of the factors, which exacerbate dyslipidemia, i.e., the increase in serum triglyceride levels in the ECh group and increase in liver cholesterol content." (PMID 32587660, 2020). "This study aimed to evaluate the association between serum vitamin D levels and nonalcoholic fatty liver disease (NAFLD) parameters, such as metabolic syndrome (MS), inflammatory cytokines (tumor necrosis factor, high sensitive C-reactive protein) and adipokines (adiponectin, leptin)." (PMID 31311491, 2019). "In situations of inflammation, common in metabolic syndrome, a variety of mediators (including tumor necrosis factor-α, interleukin 6, and interleukin 10) could have an impact on NF-κB pathway." (PMID 30945110, 2019). "Indeed, some CD8+ cell-derived cytokines, such as TNFα, are significantly elevated in a metabolic syndrome scenario, whereas those that are derived from CD4+ lymphocytes either remained unchanged or decreased (IL-4)." (PMID 31109070, 2019). "As also shown by our results, these findings indicate that upregulation of TNF-α might play a role in progression of dyslipidemia in T2DM." (PMID 31569751, 2019). "The increasing trend of IL-6 and Il-1β can be explained by antipsychotics (especially atypical antipsychotics) side effects such as metabolic syndrome in the long period, as increased levels of IL-6, IL-1β, TNF-α, IL-2, IFN-γ, and IL-4 have been reported in patients with metabolic syndrome." (PMID 31908647, 2019). "Notably, the neutralization of CX3CL1 or CCL2 activity on HUAEC led to a decrease in platelet-leukocyte endothelial adhesion in the metabolic syndrome group only after TNFα stimulation of HUAEC." (PMID 31109070, 2019). "BMI level was positively correlated with demographic factors (age, male and marriage), underlying diseases (DM, hypertension and dyslipidemia), the mental component summary (MCS) score from the SF-36, and laboratory factors (leptin, TNF-α, HS-CRP, HOMA-IR and WBC count)." (PMID 30013128, 2018).
metabolic syndrome (continued). "Therefore, we have decided to search for the relationship between the TNFα gene polymorphisms and serum levels of proinflammatory cytokines (IL-1α, IL-1β, IL-6, TNFα, IFNγ) and CRP in women with metabolic syndrome." (PMID 30383538, 2018). "Milk from diabetic mothers may also contain more inflammatory cytokines (e.g. TNF-α, IL-6) which mimic signalling pathways characteristic of dysfunctional adipocytes of metabolic syndrome." (PMID 26415764, 2017). "Excess adipocytes also means excess MCP1, which recruit further macrophages to adipose tissue, which in turn secrete further TNF-α, creating a downward self-reinforcing, obesogenic, diabetic, pro-atherosclerotic system whose ultimate result is the metabolic syndrome and cardiac disease." (PMID 27555379, 2017). "Therefore, the renoprotective effect of SYFSF is at least partially attributed to breaking the vicious circle between inflammatory response and dyslipidemia by inhibiting the TNF-α/NF-κB pathway." (PMID 28713834, 2017). "TNF-α could play a central role in pathogenesis of insulin resistance and accelerated atherosclerosis in the metabolic syndrome." (PMID 26881016, 2016). "One study suggested that asthmatic patients who were carriers of the A allele (AA and AG genotypes) of the TNF-308 G>A (rs1800629) genetic polymorphism had significantly higher serum TNF-α levels, which was also significantly associated with metabolic syndrome." (PMID 27701469, 2016). "Of major relevance is the contribution of TNF-α to metabolic syndrome." (PMID 26090072, 2015). "Following treatment with L-arabinose, metabolic syndrome rats had an obvious reduction in body weight, systolic blood pressure, diastolic blood pressure, fasting blood glucose, triglycerides, total cholesterol, serum insulin, TNF-α, and leptin." (PMID 26652604, 2015). "For example, a three month intervention study reported that a very low-carbohydrate diet (12% of energy from carbohydrates daily) resulted in more reduction in IL-6, IL-8, and TNF-alpha concentrations than did in a low-fat diet (25% fat, with 10% saturated fat) in 40 young adults with dyslipidemias." (PMID 26393645, 2015). "TNFα is known to contribute towards the pathology of metabolic syndrome and agents that could suppress TNFα effects have been touted as potential therapies against this condition." (PMID 25714093, 2015). "The tripeptides also inhibited TNFα dependent activation of NF-κB, a major pro-inflammatory signaling mechanisms that is involved in upregulation of many proteins contributing towards inflammation and metabolic syndrome." (PMID 25714093, 2015). "Our study suggests that circulating TNF-α may indeed be the link between dyslipidemia and inflammation in patients with DR." (PMID 26295054, 2015). "Thus, increased levels of adipokines and proinflammatory cytokines, such as TNF-α, have prominent roles in the pathogenesis of the metabolic syndrome." (PMID 24563869, 2014). "Interestingly, non-CpG methylation of PGC1-α was increased by tumor necrosis factor (TNF)-α or free fatty acids, which can be elevated in the metabolic syndrome and NAFLD." (PMID 25195642, 2014). "Controlling the release and activity of at least two cytokines, namely, TNF-α and IL-6, could contribute to the natural protective effects of physical activity in the metabolic syndrome." (PMID 24563869, 2014). "In this paper we briefly describe the pathophysiologic role of four important adipokines (adiponectin, leptin, TNF-α, and IL-6) in the metabolic syndrome and review some of the clinical trials that monitored these adipokines as a clinical outcome before and after exercise." (PMID 24563869, 2014). "Epidemiological studies have demonstrated an increase in plasma levels of inflammatory markers such as C-reactive protein (CRP), interleukin-6 (IL-6) and tumour necrosis factor-α (TNF-α) in patients with metabolic syndrome (MetS) and also in those with clinically overt Type 2 DM." (PMID 25276234, 2014).
metabolic syndrome (continued). "Inflammatory mediators such as TNF are elevated in metabolic syndrome." (PMID 23365487, 2013). "In clinical patients with dyslipidemia, TNFα levels were altered." (PMID 23698162, 2013). "Dyslipidemia in mice is significantly related to increased TNF-α levels." (PMID 23293629, 2012). "In these sense, we have previously showed dyslipidemia and increased body fat, high TNF-α and PAI-1 mRNA levels, and low plasma and mRNA adiponectin levels in 21-d-old offspring of rats fed a diet containing hydrogenated vegetable fat during gestation and lactation." (PMID 21266050, 2011). "It is noteworthy, that activators of PPARα had beneficial effects on altered TNF-α levels in patients with dyslipidemia, which might suggest a new therapeutic target for anti-inflammatory treatment by PC application." (PMID 21152327, 2010). "Activation of the AGE/RAGE axis has been demonstrated to correlate with increased inflammation and leukocyte recruitment as well as TNFα activity, and would provide an alternative link between dyslipidemia, endothelial activation/inflammation and diabetic retinopathy." (PMID 20856927, 2010). "It has indeed been demonstrated in numerous studies that HS and metabolic syndrome (MetS) share a core link through meta-inflammation, driven by common pro-inflammatory cytokines, such as tumor necrosis factor (TNF)-α, interleukin (IL)-1β and IL-6." (PMID 42266681, 2026). "Finally, in patients with metabolic syndrome who consumed black raspberry for 12 saw significant decreases in total serum cholesterol levels and inflammatory cytokines, including IL-6, TNF-α, CRP, sICAM-1, and sVCAM-1, ultimately improving vascular endothelial function." (PMID 41156509, 2025). "However, higher levels of IL-6 and TNF-α were associated with the Framingham Risk Score, whereas hsCRP and metabolic syndrome were not." (PMID 40713717, 2025). "Notably, salivary cytokines—such as interleukin-6 (IL-6), tumor necrosis factor-alpha (TNF-α), and interleukin-1β (IL-1β)—can be co-analyzed with SAA to assess inflammatory states associated with chronic stress, metabolic syndrome, or low-grade systemic inflammation." (PMID 40806495, 2025). "The results found that HDPs reduced medium-dose alcohol-caused dyslipidemia (significantly elevated T-CHO, TG, LDL-C), elevated liver glycogen levels, and inhibited intestinal-hepatic inflammation (significantly decreased IL-4, IFN-γ and TNF-α), consequently reversing hepatic pathological changes." (PMID 38672817, 2024). "Additionally, in the environment of dyslipidemia, the secretion of pro-inflammatory cytokines, such as IL-6 is activated, and to counteract this, the secretion of CD-16 monocytes and TNF-alpha is also increased, creating an environment in which the inflammatory response is activated." (PMID 38201008, 2024). "In the broader context of chronic diseases, dyslipidemia promotes the recruitment of inflammatory cells, such as macrophages, to affected tissues, where they release pro-inflammatory cytokines and chemokines, including TNF-α, IL-1β, IL-6, IL-8, MCP-1, VEGF, and adhesion molecules." (PMID 39457689, 2024). "However, visceral obesity is the main key factor involved in the pathogenesis of metabolic syndrome by increasing the release of pro‐inflammatory cytokines mainly TNF‐α which intricate in the induction of IR and pathogenesis of T2D, dyslipidemia and hypertension." (PMID 39644152, 2024). "However, the results still indicated that TNF-α inhibitors may improve hyperuricemia and dyslipidemia." (PMID 36902720, 2023). "Furthermore, the common mediators of dyslipidemia and dysglycemia, such as tumor necrosis factor, may alter lipid profiles." (PMID 34738737, 2022). "And it was also indicated that SUA might take part in stimulating the secretion of inflammatory markers such as C-reactive protein (CRP), interleukin (IL)-6, IL-18, and tumor necrosis factor (TNF)-alpha which are crucial to the development of metabolic syndrome." (PMID 35673358, 2022).
metabolic syndrome (continued). "Furthermore, there were significant differences between before and after subgroup analyses in the stratum of metabolic syndrome for TNF-α (SMD = − 1.42; 95% CI − 3.38, 0.55; p > 0.05) and the stratum of cardiovascular disease for IL-6 (SMD = − 0.42; 95% CI − 1.24, 0.39; p > 0.05)." (PMID 35352233, 2022). "Consistent with the dysregulation in adipokine levels, metabolic syndrome has been associated an aggravation in inflammation, and this state that is characterized by increased pro-inflammatory cytokines and acute phase reactants such as CRP, IL-6, and tumor necrosis factor alpha (TNF-α)." (PMID 32375340, 2020). ", in a study with obese animals with metabolic syndrome (MetS) receiving TTI (25 mg/Kg), demonstrated that this inhibitor reduced TNF-α plasma concentrations, independently of weight loss." (PMID 29322840, 2018). "Indeed, suppression of TNF-α has been suggested as a potential therapy against metabolic syndrome." (PMID 28972997, 2017). "Indeed, TNF-α is sufficient to induce features of the metabolic syndrome, such as insulin resistance (IR), and many chemical and genetic depletion studies have demonstrated the importance of inflammation and inflammatory macrophages in this process [recently reviewed in Ref." (PMID 27999564, 2016). "Epidemiological data have indicated that subjects with dyslipidemia are in a proinflammatory state, which is distinguished by elevated levels of cytokines, such as tumor necrosis factor-alpha (TNF-α) and IL-6 and could further promote the expression of hsCRP and CAMs." (PMID 24558466, 2014). "In particular, TNF expression, which was shown to be increased in response to pressure overload in the adult heart, might be one of the most important mediators of cardiac hypertrophy in metabolic syndrome with hypertension." (PMID 23365487, 2013). "First, markers of the inflammatory response such as tumor necrosis factor-alpha (TNF-alpha), interleukin-1β (IL-1β), interleukin 6 (IL-6), plasminogen activator inhibitor 1 (PAI1), and C-reactive protein (CRP) are strongly associated with features of the metabolic syndrome in humans." (PMID 22479352, 2012). "Thus, high TNF-α activity is likely to have contributed to dyslipidemia observed in T group." (PMID 21266050, 2011). "Their meta-analysis on patients with metabolic syndrome observed that berberine significantly reduced CRP by −1.54 mg/L, TNF-α by −1.02 pg/mL, and IL-6 by −1.17 pg/mL levels." (PMID 40006007, 2025). "Inflammation was present in metabolic syndrome rats, supported by high levels of serum TNF-α (96.88 ± 15.02 pg/mL) and IL-6 (21.38 ± 4.02 pg/mL) compared to control rats (TNF-α: 38.30 ± 8.25 pg/mL, 6.44 ± 1.50 pg/mL) (p < 0.05)." (PMID 40141836, 2025). "In agreement with Abrass’s study, we also found that the TNF-α, SREBP-1c, PAI-1, IL-6, and TGF-β mRNA levels were significantly increased in diabetic hamsters with dyslipidemia." (PMID 41012372, 2025). "Studies have shown that people with metabolic syndrome and T2DM frequently have higher levels of TNF-α, indicating a connection between prolonged inflammation and metabolic dysregulation." (PMID 40002771, 2025). "Diabetic rats also showed dyslipidemia, liver dysfunction, increased oxidative stress (↓GSH, ↑MDA), and elevated inflammatory markers (TNF-α, il-6)." (PMID 41361213, 2025). "Numerous patients with metabolic syndrome exhibit elevated inflammatory marker concentrations, including C-reactive protein (CRP), tumor necrosis factor-alpha (TNF-α), and interleukin-6 (IL-6)." (PMID 41245414, 2025). "The decline in estrogen further leads to elevated pro-inflammatory adipocytokines (TNF-α, IL-6), increased low-density lipoprotein (LDL), and heightened triglyceride levels, all of which elevate the risk of cardiovascular disease and metabolic syndrome (MetS)." (PMID 40469982, 2025).
metabolic syndrome (continued). "The toxicity is observed in the form of dyslipidemia, oxidative stress (increased MDA and NO and decreased GSH, SOD, CAT, and GST), and inflammatory responses (increased TNF-α and IL-6)." (PMID 40407528, 2025). "The patients had dyslipidemia, mild increases in HOMA-IR, circulating creatinine, inflammatory biomarkers (hs-CRP, TNF-alpha, IL-6), and indicators of fibrosis (galectin-3 and sST2)." (PMID 40299414, 2025). "Preclinical studies have shown that in NAFLD models, FXR activation upregulates SREBP1c, IRS-1, and TNF-α while downregulating AMPK, exacerbating metabolic stress, dyslipidemia, and inflammatory/oxidative stress via downstream target regulation." (PMID 40600138, 2025). "Dyslipidemia is a common finding in human patients with IBD and it can be attributed to the elevation of inflammatory cytokines such as TNF-α, interferon C, and interleukin-1 that inhibit lipoprotein lipase activity." (PMID 39195803, 2024). "Özlem Fentoğlu found significant correlations between serum and gingival crevicular fluid cytokines (IL-1β and TNF-α) and the TC/HDL ratio in patients with dyslipidemia." (PMID 38684998, 2024). "This reduces the production of pro-inflammatory cytokines such as interleukin-6 (IL-6) and tumor necrosis factor-alpha (TNF-α), thereby mitigating chronic inflammation, a central feature of metabolic syndrome." (PMID 39796335, 2024). "Studies conducted on Polish older adults have shown high clinical usefulness of the anthropometric indicator (LAP)as well as immunological indicators (TNF-α and HGBMI-1) in predictions of the metabolic syndrome." (PMID 36596839, 2023). "TNF-α and IL-6 are also related to non-alcoholic fatty liver disease (NAFLD), a hepatic repercussion of the Metabolic syndrome." (PMID 38027196, 2023). "The association between hemoglobin levels and SSI in T2DM was also observed after additional adjustment for potential confounders: age, sex, HT, current smokers, dyslipidemia, ACR, BMI, phosphorus, TNFα, IL6, and hs-CRP." (PMID 37762433, 2023). "TNF-α and G-CSF were the key cytokines involved in the mechanism of decreased embryo development potential in PCOS metabolic syndrome patients." (PMID 37693353, 2023). "Elevated levels of pro-inflammatory cytokines, such as IL-6, CRP, and tumor necrosis factor (TNF)-α, have been observed in both periodontal disease and dyslipidemia." (PMID 37711924, 2023). "In a model of dyslipidemia induced by a high-fat diet in rats, BCP treatment resulted in reduced TNF and IL-1β levels in the aorta." (PMID 37891972, 2023). "Activated ECMR also increases expression of proinflammatory adipokines, including tumor necrosis factor-α (TNFα), interleukins (ILs), and monocyte chemoattractant protein-1 (MCP-1) to directly impair insulin metabolic signaling and related metabolic syndrome." (PMID 37610001, 2023). "The correlation between Klotho and SSI was also observed even after additional adjustment for potential confounders: age, sex, HT, current smokers, dyslipidemia, ACR, body mass index (BMI), phosphorus, iFGF23, TNFα, IL6, and hs-CRP." (PMID 37686263, 2023). "Generally, ginger and its constituents are effective agents in the treatment of metabolic syndrome by reducing lipid accumulation by increasing the level of eNOS protein, VCAM1, TNFα, and ENaC." (PMID 35949312, 2022). "After the administration of salidroside, tyrosol, and hydroxytyrosol to the respective groups, the levels of ALT, XOD, TNF-α, and FMO3 in metabolic syndrome mice markedly decreased, while the levels of TBA and FXR significantly increased (p < 0.05)." (PMID 35928270, 2022). "Female participants with all types of dyslipidemia but low HDL-C showed an elevation of IL-6 and MCP-1 levels, and those with dyslipidemias and hypercholesterolemia presented higher levels of TNF-a compared to the normal participants." (PMID 36032093, 2022).